DMD (dystrophin)
Diseases named in the same sentence as DMD in open-access papers (continued):
Sharing a sentence is not in itself a finding about the gene and the disease.
Duchenne muscular dystrophy (continued). "Duchenne Muscular Dystrophy (DMD) is a genetic disorder characterized by disruptions in the dystrophin gene." (PMID 39595938, 2024). "Gentamicin was tested in Duchenne muscular dystrophy (DMD) patients and dystrophin protein was induced; however, there were severe side effects such as nephrotoxicity and ototoxicity which precluded gentamicin for long-term usage." (PMID 38891760, 2024). "Among the different types of muscular dystrophies, Duchenne muscular dystrophy (DMD) and Becker muscular dystrophy (BMD) are two related diseases, both caused by mutations in the DMD gene encoding for dystrophin." (PMID 39358550, 2024). "Currently, several FDA-approved drugs exploit this strategy for the treatment of Duchenne muscular dystrophy (DMD), including Eteplirsen, Golodirsen, Casimersen, and Viltolarsen, designed to skip selected exons from the DMD transcript." (PMID 38542364, 2024). "This is probably because the deficiency of dystrophin might not result in the increase in the relevant microRNA in the atrial myocardium of Duchenne muscular dystrophy." (PMID 39201459, 2024). "These DMD KO rabbits possessed many hallmarks of the disease, including cardiomyopathy and a high incidence of early-onset death, facilitating basic research and translational studies as a way of developing therapeutic strategies against Duchenne muscular dystrophy." (PMID 38628493, 2024). "The most severe form of dystrophinopathy, Duchenne muscular dystrophy, is a primary-muscle-wasting disorder of early childhood with a prevalence of approximately 1 in 5000 live male births, which is triggered by a variety of genetic abnormalities in the X-chromosomal DMD gene." (PMID 37509144, 2023). "We next used Duchenne muscular dystrophy (DMD) mice, which lacks the expression of Dystrophin gene, as transplant recipients." (PMID 37914731, 2023). "Duchenne muscular dystrophy (DMD) is a rare X-linked recessive neuromuscular disorder caused by mutations in the dystrophin gene that lead to absent or insufficient functional dystrophin, a cytoskeletal protein that enables the strength, stability, and functionality of myofibres." (PMID 37368924, 2023). "Antisense oligonucleotide (ASO) mediated exon skipping aims to reframe dystrophin transcripts for patients with Duchenne muscular dystrophy (DMD)." (PMID 36911945, 2023). "Much of the early progress in this area has been in Duchenne muscular dystrophy (DMD) where both exon skipping and gene editing have been used to restore dystrophin production in experimental models." (PMID 38550947, 2023). "BMD provides hope to the Duchenne muscular dystrophy (DMD) community because it provides evidence that expressing a truncated dystrophin isoform can result in a milder disease." (PMID 36628607, 2023). "Altered dystrophin expression was found in some tumors and recent studies identified a developmental onset of Duchenne muscular dystrophy (DMD)." (PMID 36900171, 2023). "However, this approach could only be used for repair of nonsense mutations toward the 3′ end of the gene where a truncated protein may retain partial functionality, such as reported in the dystrophin gene underpinning Duchenne’s muscular dystrophy." (PMID 38027060, 2023). "Duchenne muscular dystrophy (DMD) and Becker muscular dystrophy (BMD) are X-linked disorders affecting the synthesis of dystrophin." (PMID 36984439, 2023). "In summary, WGS could detect unambiguously two structural variants, in particular translocations involving the DMD gene and a region without known genes on chromosome 5 or on chromosome 19 in two girls suffering from Duchenne muscular dystrophy." (PMID 37686372, 2023). "Dystrophin was initially identified through the discovery of the gene involved in Duchenne Muscular Dystrophy (DMD), a severe muscle disease." (PMID 37384252, 2023).
Duchenne muscular dystrophy (continued). "For example, related to Duchenne muscular dystrophy (DMD), Ad-based expression of a truncated form of dystrophin restored dystrophin-related protein levels in mouse skeletal muscle." (PMID 36992407, 2023). "Antisense oligonucleotide (AON)-mediated exon skipping is a promising therapeutic approach for Duchenne muscular dystrophy (DMD) patients to restore dystrophin expression by reframing the disrupted open reading frame of the DMD transcript." (PMID 38010230, 2023). "Finally, all-in-one AdVP delivery of forced CRISPR-Cas9 heterodimers triggers robust DMD exon 51 splice site excision resulting in reading frame restoration and selection-free detection of dystrophin in muscle cells derived from Duchenne muscular dystrophy patients." (PMID 36937620, 2023). "Duchenne muscular dystrophy (DMD) and Becker muscular dystrophy (BMD) are the most common X-linked recessive muscular dystrophies caused by mutations in the dystrophin gene leading to a defective dystrophin–glycoprotein complex." (PMID 35270040, 2022). "The most recent FDA-approved ASO drug is casimersen, which is used for the treatment of Duchenne muscular dystrophy (DMD) and works by inducing the exon 45 skipping of dystrophin so functional dystrophin can be translated." (PMID 35335310, 2022). "Therapies that restore dystrophin expression are presumed to correct Duchenne muscular dystrophy (DMD), with antisense-mediated exon skipping being the leading approach." (PMID 36159597, 2022). "Mutations in the gene encoding the dystrophin protein (DMD) lead to Duchenne muscular dystrophy (DMD), where dystrophin protein is effectively absent, and Becker muscular dystrophy (BMD), where in-frame deletions typically result in production of a partially truncated dystrophin protein." (PMID 36420212, 2022). "Using dual-gRNA-mediated deletion, the mutant exon of dystrophin in Duchenne muscular dystrophy (DMD) was removed and the muscle functions were partially restored." (PMID 35383205, 2022). "The absence of dystrophin in Duchenne muscular dystrophy disrupts the dystrophin-associated glycoprotein complex resulting in skeletal muscle fiber fragility and atrophy, associated with fibrosis as well as microtubule and neuromuscular junction disorganization." (PMID 36402791, 2022). "Since studies published in high-centrality journals such as Nature revealed that the most common human muscular myopathy (Duchenne muscular dystrophy) is caused by a lack of dystrophin on the cytoplasmic surface of the skeletal muscle membrane, cytoskeleton proteins have been the focus." (PMID 36296973, 2022). "Alternatively, they can be used to restore the translational reading frame to rescue the production of a therapeutic protein as with dystrophin in Duchenne muscular dystrophy (DMD) or to switch to an alternative beneficial isoform." (PMID 35056851, 2022). "Duchenne muscular dystrophy (DMD) and Becker muscular dystrophy (BMD) are X-linked recessive neuromuscular disorders caused by variants in the dystrophin (DMD) gene." (PMID 34842620, 2021). "Duchenne muscular dystrophy (DMD) is characterized by progressive muscle weakness and motor function deterioration, which lead to loss of ambulation by the age of 12–15 years DMD is attributed to an inherited x-linked mutation in the dystrophin gene that predominantly affects male individuals." (PMID 33681102, 2021). "Moreover, a new approach was proposed for cell-based therapy for Duchenne muscular dystrophy, which is based on the use of cells called muscle side population (SP) cells to deliver genes, such as the human micro-dystrophin, showing their capability in recapitulating the myogenic lineage." (PMID 34065946, 2021). "In addition to the involvement of sarcolemmal abnormalities in highly progressive Duchenne muscular dystrophy and more benign forms of Becker muscular dystrophy, changes in the dystrophin complex are also involved in sarcoglycanopathies and alpha-dystroglycanopathies." (PMID 33540575, 2021).
Duchenne muscular dystrophy (continued). "Duchenne muscular dystrophy (DMD) and Becker muscular dystrophy (BMD) are X-linked recessive diseases, the major genetic alterations are mutations in dystrophin gene." (PMID 34922439, 2021). "HiPSC-CM generated via some of these methods have been used in the study of Duchenne muscular dystrophy, yet it has also been suggested that dystrophin is needed for hiPSC-CM maturation, and presently it is unknown whether the DAPC in hiPSC-CM forms a complete functional complex." (PMID 34805146, 2021). "In a utrophin-dystrophin DKO mouse model of Duchenne muscular dystrophy (DMD), we found upregulation of SLN expression in extensor digitorum longus (EDL), quadriceps, and diaphragm." (PMID 33732165, 2021). "During the last decade, multiple clinical trials for Duchenne muscular dystrophy (DMD) have focused on the induction of dystrophin expression using different strategies." (PMID 33407808, 2021). "Lack of dystrophin causes Duchenne muscular dystrophy and Becker muscular dystrophy." (PMID 34249494, 2021). "For instance, most patients with Duchenne muscular dystrophy (DMD; MIM #310200, 71%) show exonic deletions in the DMD gene, and only 17% of the patients show pathogenic SNVs." (PMID 34571966, 2021). "In context, Duchenne muscular dystrophy (DMD) is a notable progressive muscle-wasting disease that results from failed production of dystrophin—a protein that stabilizes the myofibers." (PMID 34778240, 2021). "Duchenne muscular dystrophy (DMD) is another genetic condition that causes a severe cardiomyopathy, particularly DCM, due to a loss of dystrophin." (PMID 35083221, 2021). "The dystrophin protein is defective in Duchenne muscular dystrophy (DMD), the most severe and frequent muscular dystrophy in children." (PMID 33096920, 2020). "Duchenne muscular dystrophy (DMD) is an X‐linked recessive disorder caused by mutations in the DMD gene (OMIM: 300,377), leading to the synthesis of a defective dystrophin protein." (PMID 32543101, 2020). "This is the case of dystrophin (14 Kb), the gene responsible for the devastating Duchenne Muscular Dystrophy (DMD)." (PMID 32455640, 2020). "The common and serious human genetic disease Duchenne muscular dystrophy (DMD) occurs due to the low expression of dystrophin." (PMID 31963121, 2020). "Similar patterns can be found in DYSTROPHIN, the culprit gene for Duchenne muscular dystrophy (DMD)." (PMID 32011235, 2020). "For instance, the drugs BMN 044/ PRO044, BMN 045/ PRO045, BMN 053/ PRO053, SRP-4053, and SRP-4053 can be used to therapy duchenne muscular dystrophy (DMD) by targeting dystrophin pre-mRNA." (PMID 31052598, 2019). "Eteplirsen (Sarepta Therapeutics, Ma) is designed to excise dystrophin exon 51 during pre-mRNA processing to restore functional protein expression in a subset of boys with Duchenne muscular dystrophy (DMD)." (PMID 31683630, 2019). "Diseases caused by mutations in a gene encoding cytoskeletal protein dystrophin are called dystrophinopathies, which include Duchenne muscular dystrophy (DMD), Becker muscular dystrophy (BMD), and DMD gene-related DCM." (PMID 31394715, 2019). "Patients with Duchenne muscular dystrophy (DMD) lack the protein dystrophin, which is a critical molecular component of the dystrophin-glycoprotein complex (DGC)." (PMID 30914715, 2019). "Mutation in the Dp71 coding region is associated with cognitive disturbances in Duchenne muscular dystrophy (DMD) patients, but the function of dystrophin Dp71 in tumor progression remains to be established." (PMID 31683640, 2019). "Interestingly, when crossed into the mdx (dystrophin null) mouse model of Duchenne's muscular dystrophy, the double knockout animals showed an amelioration of disease manifested by improved skeletal muscle morphology, a reduced number of degenerating muscle fibres and improved contractile function." (PMID 30401534, 2019). "Duchenne muscular dystrophy is a lethal disease caused by lack of dystrophin." (PMID 30278058, 2018).
Duchenne muscular dystrophy (continued). "For therapeutic purposes, this approach has been explored most extensively for Duchenne muscular dystrophy (DMD), which affects 1 in 3500 newborn boys and is caused primarily by out-of-frame deletions in the DMD gene that results in the loss of the structural muscle protein dystrophin." (PMID 29734750, 2018). "We investigated the capacity of this NGM platform to identify pathogenic SV in a series of patients diagnosed with Duchenne muscular dystrophy (DMD), due to large deletions, insertion, and inversion involving the DMD gene." (PMID 29070057, 2017). "Dystrophin is a key cytoskeletal protein coded by the Duchenne muscular dystrophy (DMD) gene located on the X-chromosome." (PMID 28028563, 2017). "In this study, NAb escaping AAVs were isolated from patients who had received AAV harboring mini-dystrophin gene during the Phase I clinical trial of Duchenne muscular dystrophy (DMD)." (PMID 28165834, 2017). "For example, the dystrophin-deficient mdx mouse, an animal model of Duchenne muscular dystrophy (DMD), showed reduced AQP4 expression in muscle cells, indicating that AQP4 interacts with the dystrophin-associated complex DAP." (PMID 29039751, 2017). "Duchenne muscular dystrophy (DMD) results from a genetic lesion in the dystrophin gene and leads to progressive muscle damage." (PMID 27977770, 2016). "Duchenne muscular dystrophy (DMD) is a rare neuromuscular disease characterized by substitutions, deletions and duplications in the dystrophin gene leading to frameshift and premature translation termination." (PMID 26796035, 2016). "Antisense oligonucleotides (AONs) in clinical development for Duchenne muscular dystrophy (DMD) aim to induce skipping of a specific exon of the dystrophin transcript during pre-mRNA splicing." (PMID 27612288, 2016). "Duchenne muscular dystrophy (DMD; OMIM reference 310200) affects 1 in 3,600–6,000 live male births and is caused by mutations (mainly large genomic deletions) in the X-linked dystrophin gene (DMD)." (PMID 27634466, 2016). "Novel therapeutic approaches are emerging to restore dystrophin function in Duchenne Muscular Dystrophy (DMD), a severe neuromuscular disease characterized by progressive muscle wasting and weakness." (PMID 25761239, 2015). "Currently, the most promising therapies for Duchenne muscular dystrophy (DMD) include two small-molecule approaches, exon skipping and stop codon read-through, both of which aim to restore the expression of dystrophin from the mutant endogenous gene." (PMID 26306629, 2015). "Currently, the most promising therapies for Duchenne muscular dystrophy (DMD) are exon skipping and stop codon read-through, two strategies aimed at restoring the expression of dystrophin." (PMID 26306629, 2015). "A variable response was also observed among Duchenne muscular dystrophy (DMD) patients carrying a PTC in the dystrophin gene and in a DMD mouse model." (PMID 24705877, 2014). "Some forms of Duchenne muscular dystrophy andcystic fibrosis, which are caused by PTC mutations in the 3′ region of the dystrophin and theCFTR genes, respectively, exemplify diseases that may benefit from such an approach (Linde &Kerem, 2008; Keeling & Bedwell, 2011)." (PMID 25319547, 2014). "Duchenne muscular dystrophy (DMD, MIM 310200), the most common and severe neuromuscular disease in humans, is caused by mutations in the dystrophin gene (DMD, MIM 300377) located on Xp21." (PMID 25614876, 2014). "In Duchenne muscular dystrophy (DMD), a genetic disruption of dystrophin protein expression results in repeated muscle injury and chronic inflammation." (PMID 25390038, 2014). "In addition, athletes will also seek advantage over their opponents using genomic medicine techniques such as exon-skipping to restore dystrophin expression in Duchenne muscular dystrophy that increases “natural” muscle size and strength possibly improving performance." (PMID 24455711, 2013).
Duchenne muscular dystrophy (continued). "Duchenne muscular dystrophy (DMD) and Becker muscular dystrophy (BMD) are X-linked recessive forms of muscular dystrophy caused by mutations in the dystrophin gene (DMD) on chromosome Xp21.2." (PMID 23601510, 2013). "In the most severe cases, such as Duchenne muscular dystrophy (DMD), the absence of dystrophin protein leads to sarcolemmar permeability, influx of calcium, and activation of proteases to cause myofiber necrosis and degeneration." (PMID 22438993, 2012). "Duchenne muscular dystrophy (DMD, OMIM 310200) is a lethal X-linked disorder caused by mutations in the dystrophin gene, which encodes a cytoskeletal protein, dystrophin." (PMID 22072915, 2011). "Similarly, our work may help in the design of truncated dystrophin molecules to be expressed, either by gene replacement or by exon skipping, in Duchenne muscular dystrophy patients who lack dystrophin." (PMID 21901138, 2011). "They include Duchenne muscular dystrophy (DMD) which is characterized by rapidly progressive muscle degeneration primary caused by lack of dystrophin, and sarcopenia which specifically refers to the irreversible decline of skeletal muscle mass, strength, and function with age." (PMID 22096509, 2011). "Duchenne muscular dystrophy (DMD), the most common of the muscular dystrophies, with an incidence of 1 in 3,500 males, is an X-linked recessive disorder resulting from a disabling mutation of the gene encoding dystrophin, a sarcolemmal protein found in skeletal and cardiac muscles." (PMID 21396105, 2011). "Thus, if functional dystrophin could be introduced into the muscles of patients with Duchenne muscular dystrophy, it might be possible to reduce their symptoms and prolong their lives." (PMID 19478831, 2009). "Besides the obvious example of Duchenne muscular dystrophy, we are intrigued by the possibility that TAT-μUtr may also be able to compensate for the loss of dystrophin in genetic or acute forms of cardiomyopathy." (PMID 19478831, 2009). "Background/Objectives: Duchenne muscular dystrophy (DMD) is a fatal, progressive neuromuscular disorder caused by mutations in the dystrophin gene, leading to the absence of functional dystrophin protein." (PMID 42194990, 2026). "Duchenne muscular dystrophy (DMD) is a progressive X-linked neuromuscular disorder characterized by the absence of dystrophin, leading to degeneration of skeletal, respiratory, and cardiac muscles." (PMID 41209090, 2026). "Duchenne muscular dystrophy (DMD) is a severe X-linked neuromuscular disorder caused by pathogenic variants in the dystrophin gene (DMD) leading to an absence or non-functional dystrophin protein." (PMID 41542555, 2026). "In mouse models of Duchenne muscular dystrophy (DMD), the absence of dystrophin greatly increases susceptibility to ECCs‐induced damage." (PMID 41572960, 2026). "Duchenne muscular dystrophy (DMD) is caused by mutations in the DMD gene, leading to the absence of dystrophin and progressive muscle degeneration." (PMID 40051178, 2025). "Duchenne muscular dystrophy (DMD) is an X‐linked disease caused by the absence of functional dystrophin in the muscle cells." (PMID 40329488, 2025). "The most common neuromuscular disorder, Duchenne muscular dystrophy (DMD), is caused by mutations in the DMD gene, resulting in a lack of dystrophin." (PMID 40747772, 2025). "Transcriptional adaptation upregulates UTRN in Duchenne muscular dystrophy (DMD) patients, as supported by several lines of evidence, including the use of splice-switching antisense oligonucleotides to induce the skipping of out-of-frame exons of the DMD gene." (PMID 39939773, 2025). "Duchenne Muscular Dystrophy (DMD) is a progressive muscular dystrophy caused by mutations in the DMD gene that result in the absence of dystrophin." (PMID 39941071, 2025).